ENSG00000265205 (novel transcript, antisense to SUPT6H)
Gene: Long non-coding RNA gene on chromosome 17 (28,670,054 to 28,672,804, reverse strand). Ensembl gene ENSG00000265205.
Gene Ontology:
Molecular function: miRNA inhibitor activity via base-pairing
Biological process: lncRNA-mediated post-transcriptional gene silencing